PIEZO1 (piezo type mechanosensitive ion channel component 1 (Er blood group))
Diseases named in the same sentence as PIEZO1 in open-access papers (continued):
Sharing a sentence is not in itself a finding about the gene and the disease.
glioma (continued). "In conclusion, PIEZO1 can be used as an indicator to assess the malignancy and prognosis of patients with gliomas, as well as a therapeutic target for clinical application following fully exploring the potential mechanism of PIEZO1 in CNS diseases." (PMID 36765838, 2023). "Glioma tumor tissue stiffening activates Piezo1 at focal adhesions, which further facilitates integrin-FAK signaling, remodels ECM, and reinforces tissue stiffening." (PMID 37864030, 2023). "Their study concluded that the stiffer mechanical microenvironment found in fly and mouse glioma models activated the mechanotransduction channel, PIEZO1, to promote glioma aggression." (PMID 36768856, 2023). "This phenomenon was conserved to mammals as the knockout of PIEZO1 suppressed the growth of glioma stem cells, inhibited tumor development, and extended the survival of a murine xenograft model." (PMID 36768856, 2023). "They showed that the level of Piezo1 expression in glioma cell lines (U251, LN319, SNB19) was higher compared to the astrocytic control cell line (HA1800)." (PMID 36173070, 2023). "In gliomas, Piezo1‐mediated mechanotransduction forms a positive feedback loop of tissue sclerosis and tumor progression (or invasion), and inhibition of Piezo1 or its downstream effectors can effectively mitigate glioma progression." (PMID 37366640, 2023). "The role of PIEZO1 in other systemic cancers has inspired researchers to explore its use as a non-invasive ultrasound therapy in neurological diseases, such as gliomas." (PMID 36765838, 2023). "RNA sequencing and microarray analyses reveal that Piezo1 expression is correlated with higher grades of glioma and worse clinical outcome." (PMID 36158191, 2022). "So far, Piezo1 were involved in proliferation and migration in gastric cancer, breast cancer, synovial sarcoma and glioma, but the function and mechanism of Piezo1 in HCC remain poorly elucidated." (PMID 35461277, 2022). "Accordingly, PIEZO1 expression was correlated with glioma malignancy, and it was evidenced that cancer progression occurs due to involvement of PIEZO1 in multiple signaling pathways affecting cell proliferation and microenvironment." (PMID 35884733, 2022). "Out of all studied treatments, SDT played a significant role in initiating the expression and function of the transient mechanically sensitive calcium channel Piezo1 in glioma cells." (PMID 35454942, 2022). "Through comparison, it is found that the H2B family gene and Piezo1 gene have many similar characteristics, such as high expression of the gene, which predicts the poor prognosis of glioma, but the current research on the H2B family gene is still insufficient." (PMID 36387186, 2022). "Taken together, our results suggest that SDT regulates intracellular calcium signals by upregulating Piezo1, by cooperating with increasing ROS, and by inhibiting glioma cells from becoming the energy supply chain for lipid metabolism under oxidative stress." (PMID 35454942, 2022). "Piezo1-mediated mechanotransduction can be applied in nervous system pathologies and in solid cancers, including in mesenchymal gliomas, which possess more treatment resistance and invasiveness." (PMID 35454942, 2022). "Researchers have also defined PIEZO1 as an oncogene in multiple human cancers like gastric cancer and glioma." (PMID 35608274, 2022). "The body senses external mechanical pressure through Piezo1, and high Piezo1 expression has demonstrated good sensitivity and specificity in predicting the degree of glioma tissue edema." (PMID 35454942, 2022). "A stiffer mechanical microenvironment elevated the expression of Piezo1 and promoted glioma aggression." (PMID 36419159, 2022). "In glioma, PIEZO1 plays a key role in pathways regulating the expression of proteins associated with ECM and ECM remodelling, thus promoting disease progression and malignancy." (PMID 34390472, 2021).
glioma (continued). "For instance, in glioma tissues, activation of Piezo1 by mechanical force upregulated extracellular matrix and stiffened the tissue, which in turn elevated Piezo1 expression to promote glioma aggression." (PMID 33558521, 2021). "In glioma cells, Piezo1 is localized at focal adhesions, reinforcing tissue stiffening, and further upregulating Piezo1." (PMID 34831037, 2021). "Genetic analysis of 1633 glioma samples revealed that higher expression of PIEZO1 was correlated with worse prognoses for patients." (PMID 34390472, 2021). "A high frequency of mutations in IDH1 and Chr1p19q was detected in gliomas with low PIEZO1 expression, while mutations in TTN, PTEN and NF1 were significantly enriched in cases with high expression of PIEZO1." (PMID 32999349, 2020). "We next investigated the association of abnormally activated signalling pathways with the expression heterogeneity of PIEZO1 in gliomas." (PMID 32999349, 2020). "High levels of PIEZO1 expression showed an association with malignant entities, including a high WHO Grade, IDH wild-type status and mesenchymal subtype gliomas." (PMID 32999349, 2020). "To investigate how PIEZO1 interacts with the tumour microenvironment and regulates glioma malignancy, we performed a computational analysis to identify the specific microenvironment-related genes that were correlated with PIEZO1 expression." (PMID 32999349, 2020). "Strikingly, the expression of all ECM-related genes that were positively correlated with PIEZO1 were significantly higher in glioblastoma (WHO grade IV) compared with low grade gliomas (WHO grade II and WHO grad III)." (PMID 32999349, 2020). "The results obtained in this study provided a clear picture in which the tumor stiffer microenvironment upregulates and activates Piezo1 to further enhance tissue mechanotransduction capacity, exacerbating glioma development and tumor cell proliferation." (PMID 32635333, 2020). "In conclusion, based on the results obtained in this study, glioma cell stiffness initiates a feedforward process wherein Piezo1 over-activation leads to cancer progression." (PMID 32635333, 2020). "We found that PIEZO1 expression was highly correlated with malignant clinical and molecular subtypes of glioma." (PMID 32999349, 2020). "PIEZO1 expression was significantly higher in glioblastoma (WHO grade IV) than in low grade gliomas (WHO grade II and WHO grade III)." (PMID 32999349, 2020). "To investigate molecular mechanism of glioma, we analysed the distinct genomic alternations in order of increasing PIEZO1 expression." (PMID 32999349, 2020). "The biological significance of PIEZO1 was explored by analysing two large sample-sized glioma cohorts." (PMID 32999349, 2020). "This is the first study to present the PIEZO1 expression pattern in gliomas based on different grading systems including 2016 WHO molecular classifications and the WHO Grade system according to the CGGA dataset and be verified by the TCGA dataset." (PMID 32999349, 2020). "The molecular mechanisms through which PIEZO1 regulates glioma malignancy involve multiple signalling pathways." (PMID 32999349, 2020). "This is the first integrative study characterizing PIEZO1 expression in whole grade glioma both molecularly and clinically." (PMID 32999349, 2020). "In conclusion, using publicly available transcriptomic and genomic profiling data, we found that PIEZO1 was upregulated in high grade glioma and predictive of a poor prognosis." (PMID 32999349, 2020). "Overall, this leads to an increase in tissue stiffening, which further promotes PIEZO1 upregulation in a reciprocal manner promoting glioma invasion and proliferation." (PMID 33177991, 2020). "IDH mutation established a glioma hypermethylation phenotype, and the deoxyribonucleic acid (DNA) structural domains spanning the Piezo1 promoter and 8000 bp upstream of the Piezo1 transcriptional start site (TSS) were also hypermethylated in IDH mutant gliomas." (PMID 40061015, 2025).
glioma (continued). "Moreover, Piezo1 is highly expressed in human glioma and serves as an independent prognostic marker for patient outcomes." (PMID 41155636, 2025). "Moreover, we found that the magnitude of these currents increased in response to the increasing magnitude of negative pressure, akin to what we observed in PIEZO1 currents from glioma cells." (PMID 40791371, 2025). "Thus more aggressive IDH wild-type gliomas are epigenetically more inclined to upregulate Piezo1 at the transcriptional level." (PMID 40061015, 2025). "It was demonstrated that all histological subtypes of gliomas, except oligodendrogliomas, showed Piezo1 overexpression compared to normal brain tissue and that the expression level of Piezo1 was positively correlated with World Health Organization (WHO) grade and histopathology." (PMID 40061015, 2025). "However, the hardened tissue microenvironment positively feeds back to PIEZO1 channels, increasing their protein expression and thus enhancing glioma cell invasion." (PMID 40535121, 2025). "Notably, after 4 weeks, mice bearing PIEZO1 KO glioma xenografts exhibited a significant reduction in glioma cell proliferation rate compared to those bearing PIEZO1 WT glioma cells from the same patient." (PMID 40791371, 2025). "It is worth noticing that Piezo1 expression levels increase with the grade of gliomas." (PMID 38581527, 2024). "Therefore, reducing Piezo1 gene using GsMTx4 can effectively mitigate the invasive effects of glioma cells on surrounding normal cells." (PMID 39539343, 2024). "Piezo1 inhibition leads to increased cell migration in non-small cell lung carcinoma and breast cancer but decreased cell migration in gastric cancer and glioma." (PMID 39759870, 2024). "In addition, high PIEZO1 expression levels were correlated with a worse prognosis in glioma patients." (PMID 38398074, 2024). "Moreover, it has also been shown that SDT-activated Piezo1 combined with ultrasound not only recruited macrophages in the orthotopically transplanted glioma model, but also increased the proportion of M1 macrophages." (PMID 38690080, 2024). "In aggressive gliomas, PIEZO1 is highly expressed and negatively correlated with patient survival." (PMID 38494915, 2024). "As presented in this work, Piezo1 has been associated with negative outcomes in the case of axon regeneration, ischemia, and glioma." (PMID 36173070, 2023). "Recently, thanks to the development of Piezo1 modulators (i.e. Yoda1, Jedi1/2 and Dooku2), it is possible to study the role of Piezo1 in the pathogenesis of various neurological diseases including ischemia, glioma, and age-related dementias." (PMID 36173070, 2023). "In addition, the expression of PIEZO1 transduces mechanical stimuli among the glioma cells, promoting tumorigenesis and development." (PMID 36765838, 2023). "Additionally, immunohistochemical analysis of PIEZO1 in 183 patients with gliomas suggested that PIEZO1, as an independent factor, has an adverse impact on the prognosis of glioma patients." (PMID 36765838, 2023). "Moreover, Piezo1 expression is closely related to the progression and poor prognosis of glioma and is activated by local mechanical forces to elevate Piezo1 expression to promote glioma aggression." (PMID 35454942, 2022). "More attention should be focused on whether a more structured mechanical microenvironment elevates Piezo1 expression to promote glioma aggression and tumor development." (PMID 35454942, 2022). "We found that Piezo1 was positively correlated with migratory capabilities of OC cells in vitro and lung metastasis in vivo, which is in agreement to the cancer-promoting role of Piezo1 as previously reported in studying gastric cancer, glioma, and osteosarcoma." (PMID 35942515, 2022). "Piezo1 overexpression may become a new prognostic biomarker for glioma patients and may be able to predict the edema extent of glioma tissues." (PMID 35454942, 2022).
glioma (continued). "It is able to successfully sense and quickly respond to the surrounding microenvironment and increase the stiffness of the extracellular matrix (ECM) and induce a mesenchymal-like phenotype in tumors, potentially making Piezo1 a viable therapeutic target for treatment-resistant and invasive gliomas." (PMID 35454942, 2022). "Recently, PIEZO1 was reported as a potential prognostic marker of glioma." (PMID 34390472, 2021). "similarly define a key mechanosignaling axis involving the PIEZO1 ion channel that has been shown to be overexpressed in a variety of cancers including all subtypes and grades of glioma signifying a potential common, evolutionarily conserved mechanosensation mechanism in cancer." (PMID 35127517, 2021). "PIEZO1 expression is correlated with increasing tumour tissue stiffness as tumourigenesis proceeds, and the function of PIEZO1 aggravates tumour cell proliferation and glioma malignancy." (PMID 32999349, 2020). "Furthermore, we performed Cox regression analyses to explore the prognostic value of PIEZO1 expression in gliomas." (PMID 32999349, 2020). "However, we still need to clarify the specific molecular mechanism of PIEZO1-related mechanical–biological transduction signalling pathways and how to modulate these molecules to regulate glioma progression." (PMID 32999349, 2020). "To explore the correlation between biological function and PIEZO1 expression in gliomas, we selected 392 genes and 368 genes, which were significantly correlated with PIEZO1 using Pearson correlation analysis (Pearson |R|> 0.35) in the TCGA and CGGA datasets, respectively, to conduct an analysis." (PMID 32999349, 2020). "Therefore, identification of the molecular and clinical correlations between PIEZO1 expression and glioma malignancy will facilitate the establishment of a potential therapeutic target and shed light on glioma treatment." (PMID 32999349, 2020). "Additionally, recent studies addressed a feedforward circuit mediated by PIEZO1 and tumour tissue mechanics to promote glioma growth." (PMID 32999349, 2020). "Based on these results, we believe PIEZO1 might play a role in the biological development of gliomas." (PMID 32999349, 2020). "Gliomas from the RNAseq and microarray sets were arranged in order of increasing PIEZO1 expression." (PMID 32999349, 2020). "As for the biological function of PIEZO1 expression in gliomas, we found that cell microenvironment-related genes that are related to ECM organization, cell adhesion, angiogenesis, cell migration and proliferation were positively correlated with PIEZO1 expression." (PMID 32999349, 2020). "Finally, high PIEZO1 expression was correlated with reduced survival time and acted as a robust biomarker for poor prognosis in gliomas." (PMID 32999349, 2020). "Furthermore, a stiffer mechanical microenvironment increased the expression of Piezo1 in glioma cells, which in turn enhanced tissue stiffness." (PMID 31290742, 2019). "Having established that PIEZO1 is a primary actuator responsible for NLGN3-mediated shedding of CSPG4, we hypothesized that blocking the PIEZO1 response in glioma would mimic loss of microenvironmental NLGN3 and affect glioma growth in vivo." (PMID 40791371, 2025). "Identifying Piezo1 as prognostic marker and low life expectancy related to its high expression in glioma patient 175 emphasizes the idea that Piezo1 could be attractive candidate for various clinical aspects of diseases including atherosclerosis in the near feature." (PMID 35173527, 2022). "Moreover, when Piezo1 was kept open, more calcium ions were able to enter the cells and combine with the lipid droplets to form a complex, affecting the lipid metabolism and preventing it from providing energy for glioma cells." (PMID 35454942, 2022).
glioma (continued). "The role of Piezo1 on cell migration is controversial, as some reports show that inhibition of Piezo1 increases cell migration, such as in breast cancer and non-small cell lung carcinoma, whereas others show inhibition in cell migration, such as in gastric cancer and glioma cells." (PMID 34822717, 2021). "Thus, PIEZO1 is positively correlated with the most relevant ECM genes in gliomas." (PMID 32999349, 2020). "Our findings indicate that PIEZO1 might play a role as a biomarker in gliomas." (PMID 32999349, 2020). "In addition, primary and recurrent glioma in the same patients showed similar PIEZO1 expression." (PMID 32999349, 2020). "Therefore, PIEZO1 appears to take part in the glioma aggressive pathophysiological process, and it can act as the essential biomarker for glioma malignancy and provides a potential therapeutic target to overcome glioma." (PMID 32999349, 2020). "Taken together, these findings support the idea that that targeting the NLGN3 pathway, including PIEZO1 and ADAM10-mediated cleavage events, represent therapeutic strategies for gliomas." (PMID 40791371, 2025). "Another study demonstrated that PIEZO1 localizes at focal adhesions to trigger integrin-FAK signaling and tissue stiffening in human gliomas." (PMID 39844465, 2025). "The analysis of a clinical database that consists of 325 gliomas cases from the CGGA dataset and 276 cases from the GSE16011 cohort showed that the expression of PIEZO1 is highly correlated with the malignancy and molecular subtypes of gliomas." (PMID 36765838, 2023). "The enhanced stiffness among glioma cells and the ECM microenvironment in turn regulates the activation of PIEZO1, facilitating the pathological process." (PMID 36765838, 2023). "The results demonstrated that among cases with KIRC (p = 0.0006), brain lower grade glioma (LGG) (p = 0.0073), LIHC (p = 0.012), LUAD (p = 0.025) and LUSC (p = 0.048), those with low level of PIEZO1 had longer survival time." (PMID 35747124, 2022). "Piezo1 knockdown cells fail to assemble focal adhesion structures which halts a positive feedback loop that otherwise allows glioma cells to remodel the local ECM, increase tissue stiffness, and further enhance Piezo1 activity." (PMID 36158191, 2022). "The Piezo1 channel was blocked early and combined with SDT treatment, recruited macrophages in the orthotopic transplantation glioma model." (PMID 35454942, 2022). "The expression of PIEZO1 was high in GBM and highly metastatic mesenchymal subtype gliomas, and it was correlated with cell microenvironment-related genes." (PMID 32999349, 2020). "This also explains why in high grade gliomas such as GBM, PIEZO1 expression is expressed at a high level." (PMID 32999349, 2020). "Here, we found that PIEZO1 was overexpressed in wild-type IDH-expressing gliomas, where it played an essential role in promoting cell viability and the aggressiveness of gliomas." (PMID 32999349, 2020). "Importantly, PIEZO1 serves as a key factor involved in sensing mechanical properties in the tumour and can regulate both tumour cells and their microenvironment to promote glioma progression, and it is also a potential therapeutic target for the treatment of gliomas." (PMID 32999349, 2020). "However, it is unknown whether PIEZO1 regulates glioma development and whether the mechanical environment in tumours interacts with the mechanosensory function of PIEZO1 to promote malignancy in gliomas." (PMID 32999349, 2020). "However, further research is needed to understand the role of Piezo1 and TRP ion channels in glioma malignancy." (PMID 40527011, 2025). "Gliomas with non-G-CIMP phenotypes had higher levels of Piezo1 expression compared to G-CIMP phenotypes." (PMID 40061015, 2025). "For example, in glioma, tumor cells specifically rely on Piezo1 for growth and proliferation, while Piezo1 is not expressed in normal glial cells." (PMID 38690080, 2024).